FOXA1 (forkhead box A1)
Diseases named in the same sentence as FOXA1 in open-access papers (continued):
Sharing a sentence is not in itself a finding about the gene and the disease.
breast carcinoma (continued). "In order to further identify the potential biological function of FOXA1 in breast cancer, we conducted GSEA analysis of KEGG pathway based on FOXA1 expression in merge data, and found 19 pathways with significant changes." (PMID 39440050, 2024). "Menin interacts with and promotes the expression of the transcription factors FOXA1 and GATA3 in ER-positive luminal breast cancer cells." (PMID 39336822, 2024). "Inhibition of OGT by miR-24 reduces the stability of forkhead box protein A1 (FOXA1), thereby inhibiting breast cancer cell invasion." (PMID 39285476, 2024). "Our results revealed the expression levels of FOXA1 and FOXM1 were significantly higher in breast cancer tissues than in normal tissues." (PMID 38608123, 2024). "Here, we found that forkhead box A1 (FOXA1), a forkhead family transcription factor, and metformin (1,1-dimethylbiguanide hydrochloride), a medication used to treat T2D, may impact hormone-receptor-positive (HR+) breast cancer (BC) tumor cell growth and metastasis." (PMID 39000600, 2024). "Although previous research suggests that both FOXA1 and GRHL2 play a crucial role in the development and progression of breast cancer, there is limited understanding of their upstream regulators." (PMID 38429368, 2024). "Next, using publicly available binding site data of ERα-associated TFs, we show that the identified core sites bound by FOXC1 in TNBC are bound by FOXA1 and NR2F2 in ER+ breast cancer." (PMID 39171293, 2024). "This is in line with previous researches in breast cancer, where GATA3/FOXA1 co-expressed in ER-positive cancers, as well as GATA3 and FOXA1 genes were the most upregulated out of their corresponding transcription factors in BRCA cancer samples." (PMID 38425344, 2024). "Here, we focus on the role of FOXA1/FOXA2 in cancers affected by steroid hormones, such as PCa, breast cancer, and liver cancer." (PMID 38605023, 2024). "In summary, the diabetes-related gene FOXA1 may play an important role in controlling the cell growth and invasion of hormone-receptor-positive breast cancer (HR+ BC)." (PMID 39000600, 2024). "Additionally, the migration and invasion of the hormone-receptor-positive breast cancer (HR+ BC) cell lines were also significantly decreased with FOXA1 KO." (PMID 39000600, 2024). "We speculated that metformin or deletion of the FOXA1 gene might contribute to a greater effect with a lower dose of tamoxifen in blocking hormone-receptor-positive breast cancer (HR+ BC) cell proliferation." (PMID 39000600, 2024). "In the present study, therefore, the statistical interaction between FOXA1 and AGR2 on breast cancer prognosis was explored." (PMID 37568077, 2023). "The Supertarget genes, FOXA1, ESR1, and GATA3, are among the most studied prognostic markers and therapeutic targets in breast cancer." (PMID 37297004, 2023). "As an example, our results showed enrichment of RUNX1, ESR1, FOXA1, and FOXM1 target genes in breast cancer type-specific GRNs." (PMID 37627195, 2023). "In their study, compared to HER2-zero breast cancer, the expression of luminal-related genes such as BCL2 and FOXA1 was upregulated in HER2-low breast cancer." (PMID 37770874, 2023). "HOXB gene family, FOXA1, SLC39A11, and SCUBE2 were found to play well-established roles in breast cancer development, and thus were the focus on our further analysis." (PMID 37293596, 2023). "We also observed coincident binding throughout the TAD of transcription factors relevant to breast cancer, including CTCF, FOXA1, ESRRA (a relative of the estrogen receptor ER), and MYC." (PMID 37541849, 2023). "MCF-7, T-47D and ZR-75-1 are luminal breast cancer lines, SKBR-3 and MDA-MB-453 are ER− but express FOXA1 and AR and are representative of the mApo subtype, with ERBB2-amplification and high expression in SKBR-3 and MDA-MB-453, respectively." (PMID 36358871, 2022).
breast carcinoma (continued). "Although GATA2 chromatin accessibility induction is less effective than FOXA1, GATA proteins facilitate binding of AR and estrogen receptor (ER) in prostate and breast cancer, respectively." (PMID 35269520, 2022). "Most importantly, data from this report taken together with other recent work point to a unidirectional pathway whereby JAM-A levels influence FOXA1 and, subsequently, HER2 expression in breast cancer settings (Model)." (PMID 35203384, 2022). "We found ER + lncRNA promoters enriched for FOXA1 and ESR1 binding sites; TFs known to drive ER positive breast cancer." (PMID 35982125, 2022). "These regions are located hundreds kbp from the capture region and co-localize with DNAse I hypersensitive sites, CTCF, FOXA1, GATA3, and ERα binding sites in breast cancer and normal breast epithelial cell lines." (PMID 35176995, 2022). "We next set out to validate experimentally if the TFs FOXA1 and GATA3 drive changes in DNA methylation in common breast cancer cell lines." (PMID 35331302, 2022). "The interaction between FOXA1 and the PI3K/AKT pathway has also been underscored in hormone sensitivity of breast cancer." (PMID 35498155, 2022). "We validated two TFs, FOXA1 and GATA3 in breast cancer cells, and found that their binding indeed mediates focal hypo-methylation." (PMID 35331302, 2022). "Among the strongest was the dependency on FOXA1 transcription factor knockout and protein levels of basigin (BSG; also known as CD147), a plasma membrane protein expressed in breast cancer cells." (PMID 35839778, 2022). "For instance, in lung cancer, FOXA1 increases expression of IGF-IR49, whilst in luminal B breast cancer, FOXA1 has been shown to regulate insulin growth factor 1 (IGF1) activity." (PMID 36446866, 2022). "ChIP-seq analyses found that super-enhancers in estrogen receptor (ER)-positive breast cancer cells co-localize with ELF5, FOXA1, and ER." (PMID 36232979, 2022). "In ER-positive breast cancer cell lines, enrichment in GATA motifs was observed in ERα and FOXA1 ChIP-Seq/Exo peaks and GATA3 silencing decreased or even abolished the recruitment of ERα at distal regulatory regions normally co-occupied with GATA3." (PMID 34831189, 2021). "It has been previously reported that the pioneers TFs FOXA1 and GATA3 mediated ESR1 binding by shaping enhancer accessibility; FOXA1 collaborates with GRHL2 and MLL3 to establish a targetable collateral pathway in endocrine therapy-resistant breast cancer." (PMID 34395436, 2021). "PITX1 has been reported in a breast cancer repressive complex that contains RARA, FOXA1, and ERα; identified prior to MegaTrans." (PMID 34215221, 2021). "We included ERα and FOXA1 (in lieu of FOXF1) based on their known relevance and protein-protein interactions in breast cancer, and PITX1 for relevance in other cancers and its novelty in ovarian cancer." (PMID 34215221, 2021). "For example, FOXA1 is known to segregate the luminal subtypes from the others, and AGR3 is a known biomarker for breast cancer prognosis and early breast cancer detection from blood." (PMID 34744522, 2021). "A recent study revealed that FOXA1 expression is negatively correlated with interferon activity and the INF-response gene expression signature in luminal breast cancer, suggesting that FOXA1 suppresses the immune response in this disease." (PMID 34680352, 2021). "FOXA1 and GATA3 have critical roles in ER + breast cancer in that these transcription factors form a regulatory network with ERα." (PMID 34238359, 2021). "As proof of principle, we performed genome editing of specific amino acids within the pioneer transcription factor FOXA1, a critical component of estrogen and androgen receptor signaling, in MCF‐7 breast cancer cells." (PMID 33666335, 2021). "In total, seven TFs (HOXC11, FOXA1, SPDEF, SOX12, HOXC10, GATA3 and TFAP2A) were annotated to the breast cancer samples." (PMID 34712617, 2021).
breast carcinoma (continued). "FOXA1, E2F3 and TFDP1 are also identified as miR‐522 targets by pulldown sequencing in breast cancer cells." (PMID 33369228, 2021). "Site-specific lysine 295 (K295) was substituted for glutamine (K295Q) in FOXA1, a critical transcription factor involved in the signaling of the estrogen and androgen receptors in MCF-7 Luminal A breast cancer cells." (PMID 34066014, 2021). "FOXA1 has been identified as an upstream regulator of ESR1 expression in mouse and human breast cancer cells and as a repressor of basal-like genes." (PMID 34831189, 2021). "Triple-negative, basal-like breast cancer cells show many mesenchymal characteristics and thus we generated stably transfected cells derived from MDA-MB-231 cells in which FOXA1 was upregulated after transfection with an expression vector." (PMID 33417085, 2021). "To further verify that these genes were regulated by these three TFs, we analyzed gene-expression data from knockdown (FOXA1 and ESR1) and over-expression (GATA3) experiments in breast cancer cell lines (see “Methods” section)." (PMID 34518541, 2021). "In this regard, Cocce and colleagues identified the GPI-anchored membrane protein, LYPD3, as a “druggable” downstream target of FOXA1 and the transcription factor, GRHL2 (Grainyhead Like Transcription Factor 2) in endocrine-resistant breast cancer." (PMID 34680352, 2021). "ZNF-337-AS1/miR-485/FOXA1 and ZNF-337-AS1/miR-485/GATA3 are other putative functional axes in the pathogenesis of breast cancer." (PMID 34094972, 2021). "Just as FOXA1 acts as a licensing factor for ER chromatin binding, FOXA1 is also required for recruitment and binding of RAR to DNA in breast cancer cells." (PMID 34680352, 2021). "Both FOXA1 and FOXM1 showed a significant upregulation in luminal A breast cancer subtype compared with normal breast tissues." (PMID 34425866, 2021). "One gene targeted by hsa-miR-584-5p – FOXA1 – and two genes targeted by hsa-miR-570-3p – ABL2 and SUB1 – have been described in previous breast cancer studies." (PMID 34512726, 2021). "The CpG sites affected are at enhancer regions with TFBS for ER-alpha, FOXA1, and GATA3, all known to be important for the luminal breast cancer phenotype." (PMID 33926515, 2021). "Therefore, inhibiting FOXA1 function in breast cancer may be beneficial for patient outcomes." (PMID 34680352, 2021). "Using TENET, biomarkers and potential oncogenic drivers of breast cancer (e.g. GATA3, ESR1, FOXA1), prostate cancer (e.g. FOXA1, HOXC6, HOXB13), and kidney cancer (e.g. GLIS1, MAF, RUNX1) have been identified." (PMID 32925947, 2020). "We chose a FOXA1 inducible lncRNA DSCAM-AS1 that expressed in lung adenocarcinoma, prostate and breast cancer specifically." (PMID 32929382, 2020). "For instance, FOXA1 and ESR1 (also known as ERα) are part of a transcriptional network responsible of the control of gene expression patterns of luminal A breast cancer." (PMID 32850701, 2020). "Through targeting forkhead box A1 (FOXA1), miR-132 shows an anti-proliferation effect on breast cancer cells." (PMID 33066509, 2020). "Our methodology is validated by some TTAGPs relevant to EC that had previously been confirmed by other authors, for example; FOXA1 was also a highly upregulated DEG, which is known to regulate oestrogen receptor binding in breast cancer." (PMID 32899298, 2020). "Among them, FOXA1 and ESR1 form part of a transcriptional network responsible of the control of gene expression patterns in luminal A breast cancer, the most common breast cancer subtype." (PMID 32850701, 2020). "Associations were also observed for the cistromes of established breast cancer transcription factors (TFs); ESR1, FOXA1, and GATA3." (PMID 31910858, 2020).
breast carcinoma (continued). "BMP4 and FOXA1 have been reportedly involved in patients with relapse-free survival (RFS) and disease-free survival (DFS) in breast cancer." (PMID 32182819, 2020). "We found prostate adenocarcinoma (PRAD), breast cancer (BRCA) and lung adenocarcinoma (LUAD) showed the most significantly elevated expression of FOXA1." (PMID 32929382, 2020). "In FOXA1-high tumor samples, a significantly higher expression of DSCAM-AS1 was found in both breast cancer and lung adenocarcinoma patients." (PMID 32929382, 2020). "Using this principle, we identified 71 lncRNAs up-regulated by FOXA1 in PRAD, BRCA, and LUAD and more than 200 lncRNAs down-regulated in T47D breast cancer cell lines after the silencing of FOXA1." (PMID 32929382, 2020). "ELF5 is a transcription factor regulating key genes e.g., FOXA1, EGFR, and MYC, and has been described as potential regulator of anti-estrogen resistance in luminal breast cancer and imatinib resistance in chronic myeloid leukemia." (PMID 32429253, 2020). "In another study in China, microarray analysis revealed differential gene expression profiles between breast cancer subtypes among which COL4A2, BMF, DUSP1, FOXA1 and MLPH were identified as potential candidate gene targets in TNBCs." (PMID 30871273, 2019). "While FOXA1 and GATA3 are significant predictors of favorable outcome in breast carcinoma (longer disease-free interval and overall survival), Nestin expression is associated with a more unfavorable prognosis." (PMID 30819139, 2019). "In our current study, we decided to combine AR, FOXA1 and the basal marker CK14 in order to better characterize the luminal-AR subgroup of feline mammary carcinomas." (PMID 31888566, 2019). "Because of limited sample size and lack of FOXA1 expression analysis in this research, more investigation is needed to clarify the molecular mechanisms underlying this association with the aim of identifying promising new ways to advance breast cancer prevention strategies." (PMID 30054444, 2019). "The MEXPRESS tool also allowed us to visualize FOXA1 expression and the methylation status according to the PAM50 breast cancer molecular classification." (PMID 31562808, 2019). "We therefore immunohistochemically stained ERα, FOXA1, and GATA3 in metastatic breast cancer specimens from various sites." (PMID 29972720, 2018). "FOXA1 and GATA3 are involved in tumorigenesis and malignant progression in breast cancer cells in close correlation with the hormonal status." (PMID 30647855, 2018). "Other negatively correlated genes include well-established markers of luminal breast cancer: GATA3, FOXA1, and PGR." (PMID 29898756, 2018). "In this study, we determined the impact of OGT on expression of EZH2 target genes FOXA1 and FOXC1, that are involved in breast cancer progression." (PMID 29864144, 2018). "Of the four biomarkers we detected, ESR1 is the only one in common with the reported signature for luminal breast cancers (ESR1, GATA3, FOXA1, XBP1, and cMYB)." (PMID 29868123, 2018). "As expected for transcription factors, clear nuclear signal intensity was observed for ERα, FOXA1, and GATA3 in the primary breast cancers as well as the metastatic samples." (PMID 29972720, 2018). "Our results confirmed the role of EZH2 in regulation of FOXA1 and FOXC1 expression in breast cancer cells but the effect of EZH2 depletion on these genes expression was cell- dependent." (PMID 29864144, 2018). "FOXA1 and GATA3, both well recognized as luminal breast cancer‐defining genes, play crucial roles in genomic functions of ERα." (PMID 29972720, 2018). "For this, we collected six ChIP-Seq datasets for FOXA1 and FOXA2 in human A549 lung adenocarcinoma cells, HepG2 hepatocellular carcinoma cells, T47D breast cancer cells, and Caco2 CRC cells." (PMID 29155818, 2017).
breast carcinoma (continued). "In summary, our findings have shown that IL-20 expression in breast cancer is regulated by a transcriptional complex composed of transcription factors, including ER(α), GATA3, and FOXA1, as well as a transcriptional elongation factor, Ell3." (PMID 28514748, 2017). "Breast cancer cell lines with molecular apocrine features showed a significant functional cross-talk between AR and HER2 that involved FOXA1 activity." (PMID 29137314, 2017). "The CpG regions defining Cluster 2 overlapped significantly with FOXA1 and GATA3 binding regions (ChIP-seq peaks) from breast cancer cell line experiments." (PMID 29123100, 2017). "It is known that TFF3 induces the expressions of AR, FOXA1, HER2 and basic fibroblast growth factor (bFGF) in vitro in various cancers such as breast cancer and melanoma cells." (PMID 28070169, 2017). "To validate the IPA model, we measured the expression of AR, FOXA1 and GSKB3 at mRNA level in 122 out of the 131 breast cancer cases." (PMID 28345661, 2017). "An exploration of the web-based genetic analysis in the present study showed that approximately 10% of breast cancers were altered in ESR1, AR, or FOXA1 genes and generally changes in genes concurrently occurred even though the frequency was low." (PMID 29137314, 2017). "The Molecular Taxonomy of Breast Cancer International Consortium (METABRIC) dataset was able to add a clinical attribute track and when the PAM50 subtype was applied, AR and FOXA1 were mainly altered in the basal subtype." (PMID 29137314, 2017). "FoxA1-positive cells in the mammary gland are known to originate in the mammary ducts rather than in the lobuloalveolar units and thus could potentially give rise to ductal tumors rather than alveolus-based tumors that occur in most mouse models of mammary cancer." (PMID 28865492, 2017). "We performed MLL3 chromatin immunoprecipitation sequencing (ChIP-seq) in breast cancer cells, and MLL3 was shown to occupy regions marked by FOXA1 occupancy and H3K4me1 and H3K4me2." (PMID 27926873, 2016). "ER,FOXA1 and GATA3 are three of the definingsignature genes consistently observed in ER+ breast cancers, and all three proteins have been shown to be required for theestablishment of an oestrogen-responsive ER complex." (PMID 26884552, 2016). "In luminal breast cancer cells, GATA3 is known to functionally interact with the TFs FOXA1 and estrogen receptor-α, leading to the potential for GATA3 mutations to alter the transcriptional network of these factors." (PMID 26922637, 2016). "We have described links among FOXA1, MLL3, and H3K4methylation, revealed by RIME, an unbiased proteomic technique that showed MLL3 to be a robust FOXA1-interacting protein in MCF-7 breast cancer cells." (PMID 27926873, 2016). "We further validated binding of the TFs GATA3, FOXA1 and ESR1 to the enhancers activated in breast cancers using publicly available ChIP-seq data." (PMID 27833659, 2016). "For example, in signal 1, rs812020 (per C-allele OR = 0.89, 95 % CI 0.87–0.91, P = 2 × 10-27) was annotated to a region bound by multiple key transcription factors for breast cancer, including GATA3 and FOXA1." (PMID 27459855, 2016). "Several basal miRNAs (miR-125b, miR-142, miR-152, miR-146b, miR-222, and miR-212) have also been predicted to target luminal factors that have been previously identified in breast cancer, including ERBB2, ERBB3, ERBB4, and FOXA1." (PMID 27845906, 2016). "To investigate chromatin reprogramming during the MET process, we utilized MDA-MB-231 breast cancer cells, in which GATA3, and its known partners, FOXA1 and estrogen receptor-α, are below limits of detection at the protein level." (PMID 26922637, 2016). "We propose a mechanism whereby the pioneer factor FOXA1 interacts with chromatin and recruits the methyltransferase MLL3, facilitating the deposition of H3K4me1 in breast cancer cells." (PMID 27926873, 2016).